CXCR4 (C-X-C motif chemokine receptor 4)
Diseases named in the same sentence as CXCR4 in open-access papers (continued):
Sharing a sentence is not in itself a finding about the gene and the disease.
prostate carcinoma (continued). "Then, the results showed that the overexpression of miR-494-3p might play a crucial role in posttranscriptionally regulating CXCR4 in human prostate cancer cells." (PMID 36003502, 2022). "In line with this hypothesis, Mimeault and Batra reported that AKT stabilizes HIF-1α and, thus, promotes HIF-1α-dependent CXCR4 expression in breast and prostate cancer cells." (PMID 34064589, 2021). "Furthermore, the CXCL12/CXCR4 axis was shown also to mediate the localizing and tethering of prostate cancer cells and of breast cancer cells to the BM and regulate their growth." (PMID 33987095, 2021). "In conclusion, prostate cancer-derived exosomes could reinforce CXCR4 expression in MDSCs through the TLR2/NF-κB signalling pathway, eventually promoting migration of MDSCs into tumor microenvironment in a CXCR4-CXCL12 axis-dependent manner." (PMID 34659412, 2021). "However, not much is currently known about the dysregulation of the chemokine receptor CXCR4 levels in prostate cancer progression." (PMID 35177982, 2021). "We first determined if activation of endogenous CXCR4 by stromal cell–derived factor 1α (SDF1α) could activate ARF1 in human androgen–insensitive prostate cancer (DU145 and PC3) cells and human embryonic kidney 293 (HEK293) cells." (PMID 34022220, 2021). "Specifically, CXCL12/CXCR4 signaling axis in prostate cancer bone metastasis (the main site of prostate cancer dissemination) participates in the formation of the endosteal niche, and blocking this axis compromises initial establishment of tumors in the bone microenvironment." (PMID 33572160, 2021). "Treg numbers are increased in prostate cancer patients with bone metastasis, and this may be due in part to active recruitment and retention of Tregs in the bone marrow by CXCR4/CXCL12-mediated signaling, a pathway that is often also upregulated in DTC." (PMID 33805598, 2021). "Specifically, data from different laboratories evidence that CXCR4 exerts its tumor-promoting effects to accelerate cancer cell proliferation, migration and invasion in ovarian cancer, glioblastoma, colorectal cancer, and prostate cancer." (PMID 34180759, 2021). "Furthermore, SLUG can promote prostate cancer cell migration and invasion via activation of the CXCR4/CXCL12 axis." (PMID 33227080, 2020). "In addition, its receptor C-X-C motif chemokine receptor 4 (CXCR4) has been used as an effective therapeutic target in prostate cancer." (PMID 33365318, 2020). "CXCR4 is the most common chemokine receptor expressed on malignant cells; it has been found in more than 23 human tumor types such as kidney, lung, brain, breast and prostate cancers." (PMID 33096815, 2020). "Since the overexpression of miR-21 and/or CXCR4 is also observed in many other cancers, such as ovarian, gastric, colonic, pancreatic, breast, and prostate cancers, our study could also shed some light on the efficacious treatment development for them." (PMID 33123586, 2020). "CXCL12/CXCR4 signalling activates MMP-9 expression in prostate cancer cells." (PMID 31718684, 2019).
prostate carcinoma (continued). "The prostate cancer cells preferentially colonized to lateral endocortical regions of the bone where osteoblasts and bone formation are increased in comparison to the medial side, and was disrupted during CXCR4 inhibition." (PMID 29642534, 2018). "Furthermore it has been shown that CXCR4 protein expression correlates with tumor grade in human prostate cancer and SDF-1 mRNA expression is elevated in metastatic prostate tumors." (PMID 28859090, 2017). "T cells have also been shown to traffic to the BM efficiently via the CXCR4/CXCL12 axis in prostate cancer patients, which implies that adoptively transferred NK cells may also be able to traffic to the BM in leukemia patients." (PMID 28915651, 2017). "Interaction between the nuclear pool of both CXCR4 and protein Gαi has been already documented in prostate cancer, and supports the hypothesis that CXCR4 may regulate the signaling from inside the nucleus." (PMID 28186979, 2017). "SDF-1α/CXCR4 signaling activates Akt1 in the lipid rafts of prostate cancer cells." (PMID 28072855, 2017). "Additionally, PIM-1 promoted prostate cancer cell migration and invasion by phosphorylating CXCR4 at Ser‐339." (PMID 27596051, 2016). "By blocking the CXCL12/CXCR4 pathway, prostate cancer bone metastasis was significantly suppressed, supporting the hypothesis that prostate tumors metastasize to the bone by adopting this bone-homing signaling pathway." (PMID 25978029, 2016). "Accordingly, previous observations have reported that PPARγ ligands downregulate CXCR4 expression in colon, lung and prostate cancer cells, however, the mechanism by which PPARγ may regulate CXCR4 expression remain largely unknown." (PMID 27556298, 2016). "In addition, using a prostate cancer model, CXCR4-dependent migration was shown to increase matrix metalloproteinase-9 (MMP-9) expression and decrease TIMP metallopeptidase inhibitor 2 (TIMP2) expression, contributing to a more invasive phenotype." (PMID 27618899, 2016). "When CXCR4 is activated, both circulating hematopoietic stem cells and prostate cancer cells have increased endothelial cell adhesion and transendothelial migration, indicating this pathway may direct metastasis." (PMID 27912752, 2016). "In addition to enhancing angiogenesis and lymphangiogenesis, Pim kinases are likely to promote metastatic prostate cancer growth by employing the CXCL12/CXCR4 chemokine pathway." (PMID 26075720, 2015). "To find out whether Pim/CXCR4 interaction plays a role also in our prostate cancer xenograft model, we first assessed whether there were differences in the phosphorylation status of CXCR4 between our stable cell lines." (PMID 26075720, 2015). "Therefore, we set out to examine how androgens regulate the subcellular localization of CXCR7 and to determine the role of this protein in CXCR4-mediated motility in prostate-cancer cells." (PMID 25884570, 2015). "Shen PF identified that miR-494 was down-regulated in prostate cancer and significantly inhibited the proliferation, metastasis, and invasion of prostate cancer cells by regulating CXCR4 which involved in many fundamental cellular process and cancer progression." (PMID 25809707, 2015). "Moreover, androgen-triggered motility of prostate-cancer cells depends on signaling by the CXCL12/CXCR7/CXCR4 axis." (PMID 25884570, 2015). "Furthermore, neutralization of CXCR4 in prostate cancer cells with anti-CXCR4 antibodies significantly reduced metastatic burden of experimental bone metastasis." (PMID 24472670, 2014). "Consistent with our earlier results indicating that CXCL8 signaling up-regulated CCR2 and CXCR4 expression in prostate cancer cells, we observed that the reduction in autocrine CXCL8 expression resulted in a significant decrease in CCR2 and CXCR4 mRNA expression in PC3-120 cells." (PMID 24970800, 2014). "This indicates that CXCR4 targeting may represent a novel, effective strategy for the treatment of human prostate cancer." (PMID 24137439, 2013).
prostate carcinoma (continued). "Many metastatic human prostate cancers also express functional CXCR4." (PMID 24259307, 2013). "Nuclear localization of CXCR4 may be a mechanism by which prostate cancer cells employ to survive, even after the insult of chemotherapy." (PMID 23468933, 2013). "The role of the SDF-1/CXCR4 axis in prostate cancer has been experimentally demonstrated." (PMID 24137439, 2013). "Collectively, these data suggest that the ‘RPRK’ motif may be involved in localization of CXCR4 to the nucleus in prostate cancer." (PMID 23468933, 2013). "While CXCR4 is present in almost all invasive cancers, CXCR5 has been implicated in advanced stages of chronic myelogenous leukemia, head and neck cancers, colon, and prostate cancer." (PMID 23773523, 2013). "Interestingly, high levels of CXCR4 are also observed in CD44+/CD133+ prostate cancer stem cells (CSC)." (PMID 24259307, 2013). "Given the frequency of PTEN gene alterations in advanced human prostate tumors and expression of CXCR4 in these patients, Akt1 signaling may be a therapeutic target for advanced prostate cancer patients." (PMID 23902739, 2013). "Likewise, expression of CXCR4 was detected in nuclear fractions among several prostate cancer cell lines, compared to normal prostate epithelial cells." (PMID 23468933, 2013). "Moreover, a previous study demonstrated that the CXCR4/CXCL12 interaction activates PI3K/AKT signaling in prostate cancer cells." (PMID 22359577, 2012). "However, little is known about the role of the CXCR4/CXCL12 signaling pathway in the maintenance of prostate cancer progenitors." (PMID 22359577, 2012). "The SDF-1/CXCR4 signaling pathway is important for prostate cancer metastasis to bone." (PMID 24213323, 2012). "Although we did not study if CXCR4 was a direct molecular target for AMP, our studies suggest that one of the molecular mechanisms by which AMP inhibits prostate cancer metastasis may be via downregulation of CXCR4 expression and function." (PMID 22693649, 2012). "Blocking of CXCR4 with a neutralizing antibody decrease prostate cancer cell invasivity, inhibits homing of prostate cancer cells to the bone and also attenuate growth of prostate cancer cells in bone." (PMID 24213323, 2012). "Our data suggest that SLUG could positively regulate the CXCL12/CXCR4 signaling in prostate cancer cells, leading to cancer migration and invasion." (PMID 22074556, 2011). "Furthermore, we determined that forced expression of SLUG increased migration and invasion of human prostate cancer cells through activation of CXCR4/CXCL12 axis." (PMID 22074556, 2011). "Knockdown of SLUG decreased CXCL12 and CXCR4 expression in prostate cancer cells." (PMID 22074556, 2011). "To investigate whether SLUG can also regulate CXCR4 expression in prostate cancer cell lines, we infected four prostate cancer cell lines with retrovirus expressing SLUG (pMig-Slug) or control retroviruses (pMig)." (PMID 22074556, 2011). "Next, we asked if endogenous SLUG is required for CXCR4 expression in prostate cancer cell lines." (PMID 22074556, 2011). "CXCR4 has also been shown to play an important role in prostate cancer cell adhesion." (PMID 21603150, 2011). "The study was the first time to report the roles of CXCL12 and CXCR4 in PNI of prostate cancer." (PMID 18983683, 2008). "Prostate cancer cells with significant CXCR4 expression may escape from primary tumor foci, enter into the lymphatic and blood vessels and migrate toward cells expressing CXCL12." (PMID 18983683, 2008). "Furthermore, antibodies that recognize CXCR4 block the metastatic spread of the prostate cancer cells to bone in an in vivo animal model." (PMID 16859559, 2006). "Based upon these observations, we hypothesized that prostate cancer (CaP) cells may use the CXCL12/CXCR4 axis to home to bone marrow." (PMID 16859559, 2006).
prostate carcinoma (continued). "Moreover, while the activation of Wnt/β-catenin and SDF-1/CXCR4 signaling was supported by molecular evidence, the precise functional consequences of pharmacological inhibition of these pathways in different prostate cancer subtypes and stromal contexts warrant further investigation." (PMID 40735647, 2025). "Therefore, anti-CXCR4 treatment in prostate cancer could be a potential alternative, and our protocol may provide a companion diagnostic test." (PMID 38727318, 2024). "The flavonol myricetin could suppress the CXCL12-CXCR4 axis in human prostate cancer cells PC-3 via inhibiting the activity of Moloney murine leukemia virus 1 (PIM1) and disrupting its interaction with CXCR4, leading to a significant decrease in CXCL12-induced cell migration." (PMID 39465008, 2024). "Interestingly, Slug can reversely elevate CXCR4 expression in human prostate cancer." (PMID 37238941, 2023). "Thus, reduced SDF-1 secretion by prostate cancer cells after depletion of platelet SCF could result in diminished mPC3 tumor growth due to inhibition of angiogenesis through effects on the SDF-1/CXCR4 pathway." (PMID 35515124, 2022). "Conversely, in prostate cancer where CXCR4 strongly regulates the development of metastasis, treatment of prostate cells with dihydrotestosterone increased the expression of the androgen receptor, CXCR4, PI3K and AKT phosphorylation as well as EMT and downstream cell cycle control genes." (PMID 35406582, 2022). "Upon the combined treatment of docetaxel and ADT, prostate cancer cells can recruit and induce the polarization of the tumor-associated macrophages to release CXCL12, which in turn promotes the survival of cancer cells via CXCR4 and mediate the drug resistance." (PMID 34069563, 2021). "In conclusion, new data were provided herein to support the hypothesis that exosomes secreted from prostate cancer could upregulate the expression of CXCR4 in MDSCs, putatively by increasing engagement of TLR2 and phosphorylation of NF-κB, resulting in MDSCs accumulation into tumor microenvironment." (PMID 34659412, 2021). "Furthermore, AKT could play a crucial role in the early phase of bone metastasis of breast and prostate cancer because the AKT signaling is strongly involved in different levels of the CXCL12/CXCR4 axis." (PMID 34064589, 2021). "However, the role of androgens in regulating CXCR4-mediated motility with respect to CXCR7 function in prostate-cancer cells remains unclear." (PMID 25884570, 2015). "The chemokine receptor CXCR4, a direct transcriptional target of KLF5, is subsequently activated and binding of its ligand CXCL12 (CXCL12, also known as SDF-1α) underlies the preferential chemotactic migration of prostate cancer cells to organ sites with elevated levels of CXCL12, for example bone." (PMID 24429391, 2014). "Our studies show that CTCE-9908 is efficacious in inhibiting total tumor burden without significantly reducing primary tumor burden suggesting that targeting CXCL12/CXCR4 axis may be therapeutically beneficial for the management of prostate cancer patients undergoing chemo or radiation therapy." (PMID 24472670, 2014). "Furthermore, CXCL8 signaling also increased the expression of CXCR4 and CXCR7 (the receptors mediating the biological activity of CXCL12) and CCR2 (a receptor activated by the ligand CCL2) in both PTEN-expressing and PTEN-deficient prostate cancer cells." (PMID 24970800, 2014). "Furthermore, identification of transport pathways required for nuclear localization of CXCR4 may reveal additional targets for therapeutic development to hinder prostate cancer metastasis and improve patient survival." (PMID 23468933, 2013). "Therefore, antagonizing nuclear transport pathways and/or the action of nuclear CXCR4, could provide a rational approach to prevention and management of prostate cancer." (PMID 23468933, 2013).
prostate carcinoma (continued). "Contrasting findings of Wang and co-workers who demonstrated that expression of CXCR7 in a CXCR4 background in prostate cancer led to faster primary tumor growth suggest that growth regulating functions of CXCL12 may depend on tumor cell origin and on the tumor environment." (PMID 24040160, 2013). "Thus CXCR4 may contribute to maintenance of prostate cancer progenitors through activation of the PI3K/AKT axis." (PMID 22359577, 2012). "Moreover, mouse xenograft studies suggest that inhibition of the CXCR4 pathway may be beneficial in the targeting of prostate cancer progenitors in vivo." (PMID 22359577, 2012). "Interestingly, CXCR4 is also a relevant molecular marker in cancer, as it is overexpressed in more than 20 human malignancies including the highly prevalent lung, breast, pancreas, ovarian, colorectal, hepatic and prostate cancers, as well as some forms of leukemia and lymphoma." (PMID 40307933, 2025). "This study aimed to investigate how CAFs regulate the stemness of prostate cancer stem cells (PCSCs), with a focus on the Wnt/β-catenin and SDF-1/CXCR4 signaling pathways." (PMID 40735647, 2025). "In prostate cancer, CTC ≥5/7.5mL predicts poorer prognosis, and CXCR4+/αvβ3+ CTCs (osteo-directed phenotype) correlate with bone colonization." (PMID 41458551, 2025). "In the prostate cancer TME, macrophages primarily polarize toward the M1 state and utilize CXCL12/CXCR4 crosstalk to chemoattract peripheral CD8+ effector T cells, which target and kill cancer cells, thereby impeding tumor progression." (PMID 40698080, 2025). "These genes, AREG, CXCR4, IL11, KITLG and OSCAR, are known to play a significant role in tumour progression and metastasis promotion of prostate cancer as well as colorectal or pancreatic cancers." (PMID 39374163, 2025). "In a myc-induced obesity-driven mouse model of prostate cancer, immunofluorescence staining of ventral prostate tissue shows high levels of CXCL12 in stromal compartments and high staining of CXCR4 and CXCR7 in tumor epithelial compartments." (PMID 41347146, 2025). "Through CXCR4-mediated signalling, the epithelial–mesenchymal transition (EMT) is also promoted, which intensifies the aggressiveness of prostate cancer." (PMID 39941741, 2025). "In the immune cell cluster of prostate cancer, formononetin targeted CD74, TNF, HBB, THBS1, INSR, CXCR4, and HSP90AA1." (PMID 38874510, 2024). "Androgens have been shown to regulate CXCR4 expression in prostate cancer cells, either directly by putative androgen-responsive elements (ARE) in the CXCR4 gene promoter, or indirectly by androgen-sensitive transcription factors." (PMID 38291527, 2024). "The use of a CXCR4 antagonistic blocker, AMD3100, or CRISPR-Cas9 knockout of CXCR4 decreased the metastatic potential of prostate cancer cells." (PMID 39596205, 2024). "Combined with its ligand CXCL12, CXCR4/CXCL12 axis increased the aggressiveness of PCa and enhanced the ability of prostate cancer cells to adhere to the extracellular matrix." (PMID 38800374, 2024). "Computational biology and in vivo verification have elaborated on the potential of MAOB to activate the CXCR4-Src/JNK signaling pathway, eventually aiding in the growth and progression of prostate cancer." (PMID 39000203, 2024). "Similar observations of reciprocal regulation of CXCR4 and CXCR7 have been made in prostate cancer cells and in neurons." (PMID 38472446, 2024). "Agonist stimulation induces heteromerization between CXCR4 and CB2 in human breast and prostate cancer cells, resulting in decreased calcium signaling and cell migration." (PMID 37749552, 2023). "In prostate cancer, estrogen-induced CAF-derived CXCL12 binds to CXCR4 and enhances mast cell proliferation, migration, and inflammatory cytokine secretion, thus exhibiting oncogenic effects." (PMID 37719863, 2023).